PDE3A (phosphodiesterase 3A)
Diseases named in the same sentence as PDE3A in open-access papers (continued):
Sharing a sentence is not in itself a finding about the gene and the disease.
cancer (27 papers, 2016 to 2025). A tumor composed of atypical neoplastic, often pleomorphic cells that invade other tissues. "A class of small molecules has recently been described that causes selective cancer cell killing by inducing complex formation between two cellular proteins, PDE3A and SLFN121–3." (PMID 34272366, 2021). "PDE3A modulators for cancer therapy cause serious side effects as they inhibit PDE3A phosphodiesterase activity, which is essential for the maturation of oocytes and the formation of platelets." (PMID 32591543, 2020). "In fact, velcrin-based SLFN12 modulation has shown significant potential for treating certain SLFN12- and PDE3A-positive cancers." (PMID 41150877, 2025). "Recent studies have highlighted PDE3A as both a biomarker and a potential therapeutic target in cancer." (PMID 41179677, 2025). "Over recent years, specifically PDE3A has emerged as a target for therapeutic intervention in cardiovascular diseases and cancer." (PMID 40497949, 2025). "Velcrins were found to have potent anticancer activity and selectively kill cancer cells with elevated PDE3A and SLFN12 expression." (PMID 39166256, 2024). "In gastrointestinal stromal tumors, compared to other types of human cancers, PDE3A and PDE3B are highly expressed, offering a promising avenue for targeted therapy." (PMID 37759695, 2023). "It has been described that small molecule compounds, which stabilize complex formation between the phosphodiesterase PDE3A and SLFN12, cause selective cancer cell killing." (PMID 35037067, 2022). "Although PDE3A is involved in the development of several cancer types but its role in GC is still unclear." (PMID 35474446, 2022). "Genotyping of the same 45 polymorphisms in 264 patients of the Italian CERP study, also treated with opioids for cancer pain, instead confirmed the association for two SNPs in ZNF568 and PDE3A genes." (PMID 31953506, 2020). "We also tested nauclefine against other PDE3A-expressing cancer cell lines, including MCF7, EKVX, and H4 cells." (PMID 32591543, 2020). "That extensive survey of hundreds of human cell lines identified cancer-cytotoxic modulators of PDE3A, epitomized by the DNMDP compound (6-(4-(diethylamino)-3-nitrophenyl)-5-methyl-4,5-dihydropyridazin-3(2H)-one)." (PMID 28454120, 2017). "Recent reports suggested the potential role of PDE3A in modulating the effectiveness of the therapeutic agent DNMDP in cancer cells." (PMID 28743736, 2017). "A recent report showed that PDE3A affects the sensitivity of cancer cell lines to the anticancer therapeutic agent DNMDP." (PMID 28743736, 2017). "Similarly, SLFN12 activity is regulated by phosphorylation, with dephosphorylation at S368 and S573, triggered through interaction with PDE3A, activating its RNase function and promoting cancer-selective cytotoxicity." (PMID 41303540, 2025). "Velcrins, a class of small molecules that act like molecular glues by inducing a heterotetrameric complex between SLFN12 and the protein phosphodiesterase 3A (PDE3A), can promote cancer cell death by stabilizing SLFN12 protein, thereby enhancing its RNase activity." (PMID 41150877, 2025). "We speculate that SLFN12 may have a similar physiological function that is leveraged by velcrins to kill cancer cells expressing elevated levels of PDE3A and SLFN12." (PMID 34272366, 2021). "This method may also aid in stratifying patients in cancers where PDE3A expression is less common." (PMID 40527986, 2025). "Future studies are warranted to define expression thresholds and to determine the frequency of PDE3A expression across various cancer types, which may help to identify patients most likely to benefit from PDE3A-targeting therapies should these modulators enter clinical use." (PMID 40527986, 2025). "In solid tumors, the protein–protein interaction between PDE3A and SLFN12 is well established in several cancer types, and the crystallized structure for this interaction has been resolved." (PMID 41150877, 2025).
cancer (continued). "The interaction of SLFN12 with the catalytic domain of PDE3A activates SLFN12, which cleaves tRNALeu and induces apoptosis and death of a large variety of cancer cells." (PMID 40497949, 2025). "DNMDP stabilizes the interaction between PDE3A and Schlafen 12 (SLFN12), inducing cytotoxicity in cancer cells with elevated expression of both proteins." (PMID 41179677, 2025). "Hypermethylation of the phosphodiesterase 3A (PDE3A) gene correlates with cisplatin resistance, and the epigenetic activation of forkhead box protein F1 (FOXF1) confers cancer stem cell properties to cisplatin resistance." (PMID 41008870, 2025). "DNMDP is a potent and selective inhibitor of PDE3A and PDE3B, effectively eliminating cancer cells by promoting interactions between PDE3A/B and SFLN12, a critical protein in this process." (PMID 37759695, 2023). "In in vitro experiments, SLFN12 cleaves rRNA as an active RNase complex with phosphodiesterase 3A (PDE3A), enhancing DNMDP (6-(4-(diethylamino)-3-nitrophenyl)-5-methyl-4,5-dihydropyridazin-3(2H)-one)-induced cancer cell death." (PMID 35768579, 2022). "Here we demonstrate that SLFN12 is also an RNase, that this RNase activity is increased by incubation with velcrin-bound PDE3A, and that SLFN12 RNase activity is essential for velcrin-induced cancer cell killing." (PMID 34272366, 2021). "DNMDP promotes phosphodiesterase 3A (PDE3A) physical interaction with SLFN12 and induces apoptosis in 766 cancer cell lines, and depleting SLFN12 decreases the DNMDP sensitivity." (PMID 34571887, 2021). "We identified several novel candidate genes (e.g., ICAM3, CCL16, PDE3A, and PRTN3) and showed that ICAM3 mediates cancer cell stemness as well as cancer-related inflammation via Src/PI3K/AKT signaling." (PMID 33500726, 2021). "DNMDP appeared to promote a neomorphic cytotoxic interaction between PDE3A and SLFN12, paving the way for a novel class of potential cancer therapeutic agents." (PMID 28454120, 2017). "In the STI-571 sensitive human cancer cell line GIST882, PDE3A expression was detected by IF and two PDE3A protein isoforms identified by Western blotting at an apparent molecular weight of 115 and 118 kDa, respectively." (PMID 28454120, 2017). "Taken together, these results support the hypothesis that SLFN12 encodes an RNase, that SLFN12 RNase activity is stimulated by DNMDP-induced complex formation with PDE3A, and that SLFN12 RNase activity is required for DNMDP-induced cancer cell death." (PMID 34272366, 2021). "Unlike other known PDE3A modulators, nauclefine does not inhibit the PDE activity of PDE3A, representing a type of PDE3A modulator that induces cancer cell death without affecting its canonical function." (PMID 32591543, 2020). "Data mining also indicated that co-occurrence of PDE3A and SLFN12 is rare in normal tissues, while their co-occurrence was found in a subset of cancer cell lines, opening the perspective of a novel class of cancer-selective cytotoxic compounds." (PMID 28454120, 2017). "Several possible explanations exist for this apparent discrepancy, such as the employed human cancer cell lines did not express PDE3A." (PMID 27927168, 2016). "Therefore, our results indicate that FCGR2A, PDE3A, and EPPK1 are the main target genes for MYBL2 and may function as novel cancer biomarkers." (PMID 35664780, 2022). "Thus, beyond demonstrating potent cytotoxic effects of an alkaloid natural product, our study illustrates a potentially side-effect-reducing strategy for targeting PDE3A for anti-cancer therapeutics without affecting its phosphodiesterase activity." (PMID 32591543, 2020). "Therefore, we speculate that allosteric modulation of SFPQ amongst other factors may affect its DNA-binding capacity in cancer cells, and changes in SFPQ expression are a critical means of regulating PDE3A expression." (PMID 28743736, 2017).
tumor (13 papers, 2017 to 2025). "In this study, we examined PDE3A expression in 173 formalin-fixed paraffin-embedded (FFPE) GIST tumor samples using a novel mouse monoclonal antibody and immunohistochemistry (IHC)." (PMID 40527986, 2025). "We conclude that PDE3A expression can be reliably assessed in archived tumor material using immunohistochemistry." (PMID 40527986, 2025). "Since the primary anti-tumor effect of PDE3A modulators depends on drug-induced PDE3A–SLFN12 complex formation, assessing co-expression of both proteins is considered important for patient stratification." (PMID 40527986, 2025). "Previous studies indicate that 90–100% of GISTs express PDE3A, and its expression is high compared with other tumor types or healthy tissues." (PMID 40527986, 2025). "PDE3A expression in different NSCLC tumor cell lines was analyzed by R software by exploring the CCLE database." (PMID 35256890, 2022). "Meanwhile, through the Sankey diagram, it was evident that PDE3A was mainly distributed in the LU65 tumor cell line of NSCLC." (PMID 35256890, 2022). "Extending these molecular insights, we show in vivo that nauclefine inhibits tumor xenograft growth, doing so in a PDE3A- and SLFN12-dependent manner." (PMID 32591543, 2020). "We also demonstrated that PDE3A was strongly overexpressed in CD44+ cells in the tumor tissues of PDAC patients." (PMID 28507327, 2017). "Studies indicated that PDE3A mediated tumor suppressive effect of anagrelide." (PMID 36159573, 2022). "Moreover, the inhibition of tumor growth by nauclefine was dependent on the expression of both PDE3A and SLFN12." (PMID 32591543, 2020). "How PDE3A recruitment of SLFN12 results in tumor cell death is still to be determined." (PMID 28421158, 2017). "Based on the literature, LOXL3, CHD7 and PDE3A could regulate the malignant behaviour of tumours." (PMID 36324258, 2022). "HLA-A staining followed a similar pattern to that of PDE3A and KIT staining, suggesting that the tumor cells were efficiently eliminated with SC ANA treatment, allowing the host animal cells – in this case, mouse – to re-populate the remaining space." (PMID 39930717, 2025). "Noticeably fewer PDE3A- and KIT-expressing tumor cells were detected in SC ANA-treated tumors, indicating a reduction of tumor cells as a drug response in resected tissue samples." (PMID 39930717, 2025). "Enrichment analysis showed four differential expression genes (DEGs) related to tumor growth pathways RASAL2, SerpinB5, UTG1A4, and PDE3A." (PMID 36159573, 2022). "We found that the tumor-inhibitory effects of QRHXF were accompanied by PDE3A downregulation, and this result was validated by qPCR, indicating a possible role of PDE3A in the QRHXF action." (PMID 36159573, 2022). "Our knowledge of the physiological functions of the PDE3A and SLFN12 pathway has just begun to emerge: from tumor suppressor to placental implant." (PMID 34707099, 2021). "However, the potential of these metabolites to act as molecular glues between PDE3A and SLFN12 remains unexplored, despite the fact that ANA drug sensitivity in tumor cells is thought to mostly correlate with these protein expression levels." (PMID 39930717, 2025). "SLFN12 and PDE3A are not known to play a role in oncogenesis or to be required for tumor maintenance, and they are not known to be essential genes for cell survival." (PMID 39166256, 2024). "PDE3A is a protein coding member of the cyclic nucleotide phosphodiesterase family which is responsible for hydrolyzing both cAMP and cGMP, whereas RARRES3 is a retinoic acid receptor responder that has been characterized as a tumor suppressor." (PMID 37398583, 2023). "Our study revealed that QRHXF could inhibit tumor growth, and this effect of QRHXF may involve PDE3A, RASAL2, SERPIB5, and UTG1A4." (PMID 36159573, 2022). "In conclusion, this study revealed that QRHXF could inhibit tumor growth in an A549 xenograft mouse model, and the target genes of QRHXF may include PDE3A, RASAL2, SERPIB5, and UTG1A4." (PMID 36159573, 2022).
tumor (continued). "Moreover, there was a significant correlation between the expression level of CD44 and PDE3A in the PDAC cell lines Panc-1, BxPC-3 and MIA PaCa-2, as well as the tumor tissues derived from PDAC patients." (PMID 28507327, 2017).
cardiovascular diseases (6 papers, 2017 to 2026). "In this sense, the present results could be useful in the future design of more specific and potent PDE3A inhibitors that may be used for the treatment of cardiovascular diseases." (PMID 29216268, 2017). "The PDE3 family is already targeted for the treatment of cardiovascular diseases with non-selective PDE3A and PDE3B inhibitors, such as milrinone or enoximone." (PMID 40497949, 2025).
heart disease (3 papers, 2020 to 2024). "Given the marked phenotype of significant right‐sided heart disease observed in the Pde3a knockout mice, our goal was to explore important central metabolic targets in PASMC that may be regulated by the Pde3 subtypes." (PMID 39435735, 2024). "Most studies so far have not investigated the role of specific PDE3A isoforms in cardiac disease, and it will be interesting to explore in the future whether the changes in the level of PDE3A expression associated with HF involve individual isoforms." (PMID 36883446, 2023).
adenocarcinoma (2 papers, 2022 to 2023). A common cancer characterized by the presence of malignant glandular cells. "In chemoresistant A549 cells, PDE3A was significantly downregulated, and high PDE3A expression was associated with favorable overall survival and progression-free survival in adenocarcinoma patients." (PMID 36159573, 2022). "High PDE3A expression improved OS and progression-free survival rates for patients with adenocarcinoma." (PMID 38077434, 2023).
infection (1 paper, 2016). The state of being infected such as from the introduction of a foreign agent such as serum, vaccine, antigenic substance or organism. "To identify the infection of human PDE3A and PDE3B, we observed the altered morphologies of SF9 cells between 48 and 96 h post-infection." (PMID 28959341, 2016).
PDE3A also shares sentences with these, for which no sentence is quoted: brachydactyly (5 papers); Arrhythmia (2); atherosclerosis (2); depression (2); type 2 diabetes (2); acrodysostosis (1); alcohol dependence (1); Arthritis (1); bladder tumors (1); brachydactyly syndrome (1); Breast tumor (1); cardioembolic stroke (1); cerebellar ataxia (1); cervical adenocarcinoma (1); colon carcinoma (1); coronary heart disease (1); endotoxemia (1); erectile dysfunction (1); essential hypertension (1); gastrointestinal tumors (1); hemorrhage stroke (1); ischemic cardiomyopathy (1); large artery stroke (1); metabolic syndrome (1); migraine (1); myxoid liposarcoma (1); ovarian carcinoma (1); preeclampsia (1); psoriatic arthritis (1); psychiatric disorder (1).
A further 5 diseases each share a sentence with PDE3A in 1 paper.